WNT16 (Wnt family member 16)
Description:
Ligand for members of the frizzled family of seven transmembrane receptors. Probable developmental protein. May be a signaling molecule which affects the development of discrete regions of tissues. Is likely to signal over only few cell diameters (By similarity).
Tractability: Antibody: its Gene Ontology location is reachable by antibodies, with high confidence; UniProt places it where antibodies can reach, with medium confidence; UniProt predicts a signal peptide or a membrane-spanning region. PROTAC: ubiquitination databases record sites on it.
Gene: Protein-coding gene on chromosome 7 (121,325,367 to 121,341,104, forward strand). Ensembl gene ENSG00000002745.
Subcellular location: Secreted, extracellular space, extracellular matrix
Pathways (Reactome):
Signal Transduction: Class B/2 (Secretin family receptors); WNT ligand biogenesis and trafficking
Gene Ontology:
Molecular function: cytokine activity; frizzled binding; signaling receptor binding
Biological process: keratinocyte differentiation; keratinocyte proliferation; negative regulation of apoptotic signaling pathway; oxidative stress-induced premature senescence; positive regulation of gene expression; positive regulation of JNK cascade; positive regulation of phosphatidylinositol 3-kinase/protein kinase B signal transduction; replicative senescence; Wnt signaling pathway; canonical Wnt signaling pathway; cell fate commitment; neuron differentiation; optic cup formation involved in camera-type eye development
Cellular component: cytoplasm; extracellular region
Genetic constraint (gnomAD): Loss-of-function variants: 20 observed, 36.16 expected, observed/expected ratio (o/e) 0.55, 90% interval 0.39 to 0.8. The upper end of that interval is the gene's LOEUF score, 0.8, which puts it in group 3 of 6, group 1 being the genes least tolerant of losing a copy. Missense variants: 461 observed, 476.27 expected, observed/expected ratio (o/e) 0.97, 90% interval 0.9 to 1.04. Synonymous variants: 180 observed, 187.89 expected, observed/expected ratio (o/e) 0.96, 90% interval 0.85 to 1.08.
Homologues: Orthologues: chimpanzee WNT16 (99% identical), macaque WNT16 (99% identical), rabbit WNT16 (93% identical), pig WNT16 (93% identical), guinea pig WNT16 (92% identical), mouse Wnt16 (90% identical), rat Wnt16 (90% identical), dog WNT16 (89% identical), tropical clawed frog wnt16 (76% identical), zebrafish wnt16 (66% identical), Caenorhabditis elegans egl-20 (40% identical), Drosophila melanogaster Wnt4 (35% identical). Paralogues in human: WNT7B (43% identical), WNT2B (41% identical), WNT7A (41% identical), WNT2 (40% identical), WNT3 (40% identical), WNT4 (39% identical), WNT5B (39% identical), WNT3A (39% identical), WNT5A (38% identical), WNT1 (38% identical), WNT9B (36% identical), WNT10A (35% identical), and 6 more.
Diseases named in the same sentence as WNT16 in open-access papers:
WNT16 is named in the same sentence as 61 diseases in open-access papers, as found by Europe PMC text mining. Sharing a sentence is not in itself a finding about the gene and the disease. The quoted sentences say what the papers report.
osteoporosis (18 papers, 2016 to 2026). A condition of reduced bone mass, with decreased cortical thickness and a decrease in the number and size of the trabeculae of cancellous bone (but normal chemical composition), resulting in increased fracture incidence. "The WNT16 gene's polymorphism seems to be highly related to the pathophysiology of osteoporosis, making it an attractive target for further investigation into the genetic causes of fracture risk." (PMID 38090417, 2023). "Our interest in wnt16 as a candidate causal gene underlying pleiotropy at the CPED1-WNT16 locus was based on data that supported WNT16 as a causal gene underlying locus associations with osteoporosis-related traits." (PMID 36346812, 2022). "WNT16 has been linked to bone fragility and osteoporosis in human genome wide‐association studies, as well as the functional hematopoiesis of leukocytes in vivo." (PMID 33778326, 2021). "Many studies have reported that WNT16 expression is strongly associated with bone mineral density, suggesting that WNT16 is a therapeutic target for bone loss-related diseases such as osteopenia or osteoporosis." (PMID 34879876, 2021). "Multiple studies have associated mutations in WNT16 with osteoporosis and fracture susceptibility phenotypes in humans,(121‐4) but less is known about the pathophysiological influence of WNT16 on bone during fracture repair." (PMID 33778326, 2021). "SNPs in associated regions on chromosomes 7 and 11 are proximal to genes PLEKHB1 (chr11), FAM3C (chr7), and WNT16 (chr7), and the latter has been associated with bone mineral density, osteoporosis, and fracture risk." (PMID 27325353, 2016). "In the pathogenesis of osteoporosis, polymorphism of WNT16 gene seems highly relevant." (PMID 38090417, 2023). "In addition, rs2908007 (an osteoporosis GWAS variant located in the Wnt16 promoter) confers G-allele-specific transcriptional modulation via TBX5/TBX15, USF3, and TWIST1/TCF12." (PMID 36619549, 2022). "As a ligand of Wnt signaling pathway, wnt16 is related to bone mineral density, cortical thickness, bone strength, and fracture risk, and this molecule might be an attractive target for pharmacologic intervention in treating osteoporosis." (PMID 34206401, 2021). "We clearly demonstrated that WNT16 is crucial for cortical bone homeostasis both in young adult and old mice, supporting the notion that treatment strategies targeting the regulation of WNT16 might be useful to reduce fracture risk at cortical bone sites in old patients with osteoporosis." (PMID 29530924, 2018). "Next, we analysed six selected SNPs in 631 patients evaluated for osteoporosis [rs2707518 (CPED1/WNT16), rs3779381 (WNT16), rs115242848 (LOC101927709/EN1), rs10239787 (JAZF1), rs603424 (PKD2L1) and rs6968704 (JAZF1)]." (PMID 37831088, 2023). "WNT16 is actively being investigated as a potential therapeutic target for osteoporosis, raising questions regarding the potential role of wnt16 in adult muscle." (PMID 36346812, 2022). "This new finding undoubtably consolidates the scientific foundation of Wnt16 as a therapeutic target for acquired or age-related bone diseases, such as osteoporosis." (PMID 36619549, 2022). "In order to explore the molecular mechanism of the wnt16 as a potential target for the treatment of osteoporosis, we established a zebrafish wnt16 gene knockout model, and investigated the change in phenotype of skeletal development." (PMID 34206401, 2021). "As we want to determine the possible usefulness of WNT16 as an osteoporosis drug target, it is crucial to determine if WNT16 exerts important effects on cortical bone homeostasis in adult and old mice." (PMID 29530924, 2018). "As we aimed to determine the possible usefulness of WNT16 as an osteoporosis drug target, it was crucial to determine if WNT16 exerts important effects on cortical bone homeostasis in adult and old mice." (PMID 29530924, 2018).
osteoporosis (continued). "WNT16 genome-wide association study (GWAS) meta-analyses have shown that polymorphisms of the WNT16 locus are strongly associated with cortical bone thickness, BMD, and risk of osteoporosis fracture in humans." (PMID 34879876, 2021). "Our results suggest that the therapeutic application of T-MSCs expressing high levels of WNT16 could be efficacious in treating osteoporosis." (PMID 31582989, 2019). "In addition, mouse models of osteoporosis and/or bone fracture should be used to examine differences in the treatment efficacies of T-MSCs expressing high versus low levels of WNT16." (PMID 31582989, 2019). "Moreover, WNT16 is actively being explored as a target for osteoporosis therapies, thus our study could have implications with regard to the potential of targeting WNT16 to treat bone and muscle simultaneously." (PMID 36346812, 2022). "In addition, local WNT16 treatment in rat tibiae enhanced BMD, suggesting that treatments targeting the regulation of WNT16 in bone might be beneficial for patients with osteoporosis." (PMID 32140758, 2020). "Therefore, we examined monoclonal cells prone to differentiation into osteoblasts and identified WNT16 as a biomarker that could serve to select MSCs for stem cell therapy for bone-related diseases such as osteoporosis." (PMID 31582989, 2019). "Therefore, targeting Wnt16 signaling in osteoblasts represents a promising approach to enhance the natural repair processes of bone fragility fractures and bone-destructive diseases such as RA, osteoporosis, and periodontitis." (PMID 26861315, 2016). "Thus, examination of WNT16 expression as a selection criterion prior to the clinical application of MSCs may enhance the therapeutic efficacy of stem cell therapy for bone-related complications, including osteoporosis." (PMID 31582989, 2019). "Our objective has been to study in detail the allelic architecture of three Wnt pathway genes: WNT16, DKK1 and SOST, in the context of osteoporosis." (PMID 30026596, 2018). "From this list, we selected the five SNPs with the lowest p-values for further analyses in patients evaluated for osteoporosis: rs2707518 (CPED1/WNT16), rs3779381 (WNT16, intron 1), rs115242848 (LOC101927709/EN1), rs10239787 (JAZF1, intron 2), and rs603424 (PKD2L1, intron 2)." (PMID 37831088, 2023). "Thus, if WNT16 would only have had an effect during early development but not in adult mice, this would mean that WNT16 never will be an interesting osteoporosis drug target as the osteoporosis treatment should be effective in relatively old patients with osteoporosis." (PMID 29530924, 2018). "Thus, if WNT16 only would have an effect during early development, but not in adult or old mice, this would mean that WNT16 never will become be an interesting osteoporosis drug target as osteoporosis treatment is given to relatively old subjects." (PMID 29530924, 2018).
osteoarthritis (9 papers, 2013 to 2023). A noninflammatory degenerative joint disease occurring chiefly in older persons, characterized by degeneration of the articular cartilage, hypertrophy of bone at the margins and changes in the synovial membrane. "Wnt16 has been linked to the relationship between hip geometry and the risk of osteoarthritis onset." (PMID 28684625, 2017). "Interestingly, mutations in Wnt16 were recently identified as highly significantly associated with risk of fracture, whereas Wnt16 was found to inhibit chondrocyte hypertrophy and be protective against osteoarthritis progression." (PMID 37410754, 2023). "Our study builds on these findings to suggest that the relationship found between osteoarthritis risk, joint shape and Wnt16 may stem from its role in activating early joint cell behaviours that affect the functional joint shape." (PMID 28684625, 2017). "In this study, we evaluated Wnt16 expression and its biological effects on mouse articular chondrocytes (ACs), since these cells are key to the development of osteoarthritis." (PMID 37109407, 2023). "More importantly, local Wnt16 treatment has been shown to ease osteoarthritis, inhibit bone resorption, and promote new bone formation in bone defect models." (PMID 36619549, 2022). "In recent years, further studies have shed light on the role of Wnt16 a positive regulator of bone mass and protective regulator of osteoarthritis progression." (PMID 36619549, 2022). "Wnt16 is upregulated in joints with moderate to severe osteoarthritis along with increased nuclear β-catenin expression." (PMID 28684625, 2017). "Considering the transient induction of Wnt16 and activation of Wnt/β-catenin pathway at the early stage of osteoarthritis, it is plausible to assume that Wnt16 mediates the response to neural tissue injury via promotion of β-catenin signaling." (PMID 27480121, 2016). "An upregulation of Wnt16 has been observed in osteoarthritis and injured cartilage." (PMID 24002865, 2013). "Thus, Wnt16 is now a potential therapeutic target for skeletal diseases and osteoarthritis." (PMID 36619549, 2022). "In contrast, Wnt16 maintains a balanced canonical WNT signaling and prevents the development of osteoarthritis (OA)." (PMID 38033331, 2023).
leukemia (6 papers, 2006 to 2022). A malignant (clonal) hematologic disorder, involving hematopoietic stem cells and characterized by the presence of primitive or atypical myeloid or lymphoid cells in the bone marrow and the blood. "Given recent evidence that WNT16 plays a role in the specification of hematopoietic stem cells and in human leukemia, it is important to elucidate such mechanistic properties of Wnt16 signaling." (PMID 23516471, 2013). "Thus, they suggest that the high Wnt16 and β-catenin levels play a crucial role in the leukemia-stroma interaction instead of mediating high canonical Wnt signaling." (PMID 27571104, 2016). "WNT3 and WNT16 specifically increased in chronic lymphocytic leukemia (CLL), indicating the specificity of WNTs in leukemia." (PMID 35850748, 2022). "However, several pre-B leukemia cell lines studied do not express Wnt16, suggesting a distinct role for this factor in early B lymphopoiesis that is turned off during leukemiagenesis, except in cases where Wnt16 is aberrantly activated by the E2A-Pbx1 fusion protein." (PMID 16808837, 2006).
chronic lymphocytic leukemia (5 papers, 2020 to 2023). "Wnt members, including Wnt3, Wnt4, Wnt5B, Wnt6, Wnt7B, Wnt9A, Wnt10A, Wnt14 and Wnt16, are highly expressed in chronic lymphocytic leukaemia B cells." (PMID 33417298, 2021). "In an Eμ-TCL1 mouse model of chronic lymphocytic leukemia, it was described that Wnt16, Wnt10a, Fzd1 and Fzd6 are pronounced increased in CD5+ B cells." (PMID 33659046, 2021). "For instance, epigenetic inactivation of SERP genes allowed constitutive Wnt signaling pathway in colorectal cancer, while overexpression of Wnt genes (Wnt 3, Wnt5b, Wnt6, Wnt10a, Wnt14, and Wnt16) activated Wnt signaling pathway in Chronic lymphocytic leukemia." (PMID 32904598, 2020). "It has been shown that in B-cells of Chronic Lymphocytic Leukemia (CLL), mRNA related to Wnt elements is overexpressed, such as WNT3, WNT5B, WNT6, WNT10A, WNT14, WNT16 or FZD3." (PMID 37237497, 2023).
prostate carcinoma (5 papers, 2016 to 2025). A carcinoma that arises from epithelial cells of the prostate gland. "ONC201 significantly downregulated CSC-related genes ABCB5, ALDH1A1, ALDH7A1, WNT16, CD133 and NANOG in DU145 prostate cancer cells." (PMID 28767654, 2017).
basal cell carcinoma (3 papers, 2015 to 2023). A carcinoma involving the basal cells. "For example in MRC-5 fibroblasts, genes PGR and ADH1B belonging to pathways “Oocyte meiosis” and “Propanoate metabolism” were the only genes which were up-regulated and Wnt16 belonging to “Basal cell carcinoma” pathway was the only gene which was down-regulated with a log2 fold change >1." (PMID 26380578, 2015). "The role of WNT16, a part of the canonical WNT signaling pathway family of genes, in cancer progression remains unknown, although expression of WNT16 is downregulated in Basal cell carcinoma." (PMID 34796107, 2021).
bladder cancer (3 papers, 2022 to 2025). "Quercetin-loaded nanoparticles downregulated Wnt16 and synergistically inhibited bladder cancer in a stroma-rich bladder cancer model with cisplatin NPs." (PMID 40124335, 2025). "The NP formulation significantly downregulated Wnt16 and yielded synergistic anticancer action with cisplatin NPs in stroma-enriched bladder cancer." (PMID 35701781, 2022).
Osteopenia (3 papers, 2021 to 2025). Osteopenia is a term to define bone density that is not normal but also not as low as osteoporosis. "Based on the report that Wnt16 regulates bone morphology in mice, we assessed the effects of Wnt16 on peri-implant bone formation in a rat model of disuse osteopenia." (PMID 39937002, 2025).
amyotrophic lateral sclerosis (2 papers, 2022 to 2024). Amyotrophic lateral sclerosis (ALS) is a neurodegenerative disease characterized by progressive muscular paralysis reflecting degeneration of motor neurons in the primary motor cortex, corticospinal tracts, brainstem and spinal cord. "The strongest association in our genome-wide association study (GWAS) implicated WNT16, a gene previously linked with neurodegenerative diseases such as Alzheimer, and Parkinson disease, and amyotrophic lateral sclerosis." (PMID 39574607, 2024). "Moreover, several potential disease-causing genes were detected and markedly enriched in the pathways of neurodegeneration (including WNT16, RYR3 and RYR1 genes) and amyotrophic lateral sclerosis (ALS, including NUP205, CAPN2, and NUP214 genes)." (PMID 35355568, 2022).
autoimmune disease (2 papers, 2019 to 2021). A disorder resulting from loss of function or tissue destruction of an organ or multiple organs, arising from humoral or cellular immune responses of the individual to their own tissue constituents. "miR-374b was previously found to inhibit cell growth and promote apoptosis in T cell lymphoblastic lymphoma via suppression of AKT1 and Wnt-16, which were correlated with immune activities in autoimmune diseases." (PMID 34036107, 2021). "Interestingly, WNT16 is downregulated in several autoimmune diseases including lupus and arthritis." (PMID 31781116, 2019).
breast carcinoma (2 papers, 2017 to 2022). "Taxotere-treated CAFs were shown to have higher expression of WNT16, and knockdown WNT16-expressed CAFs co-cultured with breast cancer cells significantly increased the sensitivity to taxotere chemotherapy treatment." (PMID 36550571, 2022). "So, WNT16 expression in CAFs might be contributed to chemoresistance in breast cancer cells." (PMID 36550571, 2022).
colorectal cancer (2 papers, 2020). A primary or metastatic malignant neoplasm that affects the colon or rectum. "Although we do not present data in support of this hypothesis in this study, the frequency in which WNT16 is mutated in BRAF mutant colorectal cancers may provide an impetus for investigating whether WNT16 has a role in determining sensitivity to WNT-ligand inhibitors." (PMID 32384699, 2020). "WNT16 and MEN1 may be novel drivers of aberrant WNT signaling in colorectal cancer." (PMID 32384699, 2020).
gastric cancer (2 papers, 2019 to 2024). A primary or metastatic malignant neoplasm involving the stomach. "Furthermore, compared normal tissues, the expression of Wnt-16 was upregulated in tumoral tissues, indicating that Wnt-16 may be associated with the progression of gastric cancer." (PMID 31608065, 2019).
glioma (2 papers, 2017 to 2020). A benign or malignant brain and spinal cord tumor that arises from glial cells (astrocytes, oligodendrocytes, ependymal cells). "In the present study, we also revealed that increased mRNA expressions of WNT16 was associated with shorter OS in patients with glioma, while the increased mRNA expressions of WNT3 and WNT5B were associated with longer OS." (PMID 32181818, 2020). "The survival analysis revealed that the higher expressions of WNT5A and WNT16 were associated poor overall survival (OS) in patients with glioma." (PMID 32181818, 2020). "Higher mRNA levels of WNT5A and WNT16 were significantly associated with poor OS in patients with glioma." (PMID 32181818, 2020).